LCN2 (lipocalin 2)
Diseases named in the same sentence as LCN2 in open-access papers (continued):
Sharing a sentence is not in itself a finding about the gene and the disease.
colitis (continued). "Lcn2, as an antimicrobial peptide, has been shown to preserve healthy gut microbial structure in a colitis mouse model." (PMID 34572499, 2021). "Other groups have previously demonstrated that S100A9 and Lcn2 are upregulated in the colon of mice with colitis." (PMID 34758843, 2021). "Two weeks after human fecal inoculation, elevated levels of fecal lipocalin-2 were observed (compared to basal lipocalin-2 levels of ~3 ng/g feces material), indicating the onset of moderate to severe colitis." (PMID 34050144, 2021). "While our study was performed, some reports on the role of LCN2 in other colitis were published except UC, including collagenous colitis and necrotizing enterocolitis." (PMID 35111677, 2021). "A fecal pellet from a mouse with acute DSS colitis was used a positive control, and in line with other studies displayed a signal of over 2000 pg/mg Lcn-2." (PMID 34923573, 2021). "were sufficient to induce colitis and right-sided tumors, and the authors demonstrated that Lcn2 impacted the in vitro growth of Alistipes spp." (PMID 34583649, 2021). "General signs and histological features of colitis, fecal lipocalin-2 and pro-inflammatory KC cytokine levels, global mucosa-associated microbiota, were analyzed." (PMID 33919372, 2021). "The responsiveness of LCN2 in the gastrointestinal tract was first demonstrated in colitis-induced models." (PMID 34578967, 2021). "The concentration of LCN2 is elevated in faecal material of mice subjected to dextran sulfate sodium induced colitis or when fed high-fat and salt diets." (PMID 32790727, 2020). "We assessed colitis by measuring body weight, colon length, histopathology and fecal lipocalin-2 (Lcn2), a marker of intestinal inflammation." (PMID 33027280, 2020). "The elevated level of inflammation cytokines IL-6, TNF-α, IFN-γ in colon, and LCN2 in feces and serum of colitis mice were decreased by miR-125a and miR-125b agomir injection." (PMID 32733020, 2020). "The level of inflammation cytokines TNF-α, IFN-γ, and IL-6 of the colon tissue and lipocalin-2 (LCN2) of feces and serum were significantly elevated in colitis mice." (PMID 32733020, 2020). "In accordance, increased amounts of colonic TNF-α and lipocalin-2 in FFD mice further demonstrated the protective effect of dietary cellulose on DSS-induced colitis." (PMID 33079623, 2020). "LCN-2 knockout mice harbor colitogenic bacteria, and this protein has been reported to reduce intestinal inflammation in the IL-10-knockout model of colitis." (PMID 31311100, 2019). "We first confirmed that PI3Kp110δD910A/D910A mutant (PI3KδD910A) mice in SPF conditions spontaneously develop colitis beginning at the age of 14 weeks or older based on serial fecal lipocalin-2 (f-Lcn) levels." (PMID 31546615, 2019). "Fecal Lcn-2 has been demonstrated by others to be significantly increased in DSS colitis models potentially serving as a sensitive and non-invasive approach to detect intestinal inflammation." (PMID 30936879, 2019). "Accordingly, at the end of the experiment, FoxP3CreTBX21fl/fl mice were characterized by milder colitis than controls, as shown by the histology score and the lower expression of the neutrophil-related marker lcn-2 mRNA." (PMID 31572375, 2019). "This increase, which reflected the development of colitis, was found to be time-dependent, with the Lcn-2 concentration on day 127 being 30-fold higher than that on day 40 (5139 ng/g versus 170 ng/g of feces, respectively)." (PMID 28566745, 2017). "Mice treated for 7 days with 3% DSS developed acute colitis, as evidenced by their fecal Lcn-2 levels." (PMID 28566745, 2017). "Lcn2/IL-10 double-KO mice showed a more rapid onset and development of colitis compared to IL-10 KO mice." (PMID 27734904, 2016). "Here we investigated the role of Lcn2/NGAL in intestinal inflammation using a spontaneous mouse colitis model, interleukin-10 knock out (IL-10 KO) mice." (PMID 27734904, 2016).
colitis (continued). "Further, data from bone marrow chimera showed that immune cell-derived Lcn2 is the major contributor in conferring protection against colitis." (PMID 27500193, 2016). "Transfer of Lcn2-repleted macrophages prevented the development of colitis in Lcn2/IL-10 double-KO mice in vivo." (PMID 27734904, 2016). "Restoring Lcn2 expression in intestinal macrophages by transfer of IL-10KO-derived TEPMs attenuated colitis in 4-week-old Lcn2/IL-10 DKO mice." (PMID 27734904, 2016). "Selective epithelial ablation of PPARγ dramatically increased Lcn2 expression and its secretion after S. Typhimurium challenge, confirming the importance of epithelium-derived PPARγ in colitis." (PMID 24465207, 2014). "Subsequent detailed analysis revealed that colitis severity was coupled with elevated levels of antimicrobials like Lcn2, which stabilized the pro-inflammatory endopeptidase MMP-9 in the intestinal milieu." (PMID 24465207, 2014). "When mice were challenged with 3% DSS in drinking water to induce acute colitis, we first observed that NLRX1−/− mice exhibited increased susceptibility as evidenced by histopathological analysis and quantification of fecal lipocalin-2, a marker of colitis." (PMID 24867956, 2014). "To validate the observed involvement of Lcn2 in S. Typhimurium-induced colitis, we next checked for colitis induction in streptomycin-pretreated Lcn2−/− mice mock- or S. Typhimurium-infected for 24 h." (PMID 24465207, 2014). "Remarkably, when exposed to S. Typhimurium, Lcn2-null mice exhibited a drastic reduction of the colitis and remained protected even at later stages of infection." (PMID 24465207, 2014). "S. Typhimurium-induced colitis is accompanied by elevated luminal concentrations of several antimicrobial proteins, including lipocalin-2, calprotectin, regenerating islet-derived 3 gamma (RegIIIγ) and RegIIIβ." (PMID 23028318, 2012). "Results from our laboratory and others have shown systemic upregulation of Lcn-2 (also known as siderocalin, uterocalin and 24p3) in various murine models of colitis, including human IBD." (PMID 22957064, 2012). "We next examined fecal Lcn-2 levels in IL-10 KO mice, which are prone to developing spontaneous colitis with the extent of colitis exhibiting great variability in different vivaria." (PMID 22957064, 2012). "Our results demonstrate that fecal Lcn-2 levels provide a stable, rapid, sensitive and broadly-dynamic means to non-invasively detect both low-grade inflammation and robust (i.e. classic) colitis." (PMID 22957064, 2012). "Furthermore, the concentration of lipocalin-2 (Lcn-2) was significantly elevated in TNBS-induced colitis." (PMID 40565241, 2025). "The prominent elevation of kidney Lcn2 mRNA expression in colitis mice at both study timepoints emphasize its sensitivity in detecting early tubular injury, whereas Kim‐1 was only elevated at the later timepoint consistent with its dependency in disease severity." (PMID 40018982, 2025). "In addition to colitis and ileitis, Casp8ΔIEC mice demonstrated an increased expression of the inflammatory genes Tnf and Lcn2 in the liver, suggesting mild hepatic inflammation as previously reported." (PMID 40498017, 2025). "Our results show that Lcn-2 concentration was significantly higher in TNBS-induced colitis." (PMID 40565241, 2025). "These symbionts were exclusively enriched in the control group in our study, where they exhibited strong negative correlations with pro-inflammatory cytokines (IL-6, TNF-α) and inflammation-related genes (Lcn2, Mmp3), suggesting their protective role in mitigating colitis severity." (PMID 40356657, 2025). "LCN2 has also been found to have a role in colitis-mediated colorectal cancer (CAC)." (PMID 39839775, 2024). "Furthermore, increased expression and activation of LCN2 have been observed in patients with UC, suggesting its potential regulatory effect on colitis by mediating ferroptosis." (PMID 39300068, 2024).
colitis (continued). "Furthermore, our results demonstrate that the expression of genes related to the pathogenesis and diagnosis of colitis such as Il1β, Lcn2, S100a8 and S100a9 were specifically enhanced in Socs3-deficient neutrophils localized to the colon and spleen." (PMID 37283760, 2023). "Lifetime cumulative Lcn2 levels correlated with histopathological features of colitis at 12 mo." (PMID 37526424, 2023). "Lcn-2 prevents intestinal inflammation and spontaneous colitis in IL-10 null mice by enhancing phagocytic bacterial clearance in macrophages and changing microbial composition, suggesting a protective role in colitis." (PMID 36341389, 2022). "Thus, Ent immunization protected mice from the development of colitis by limiting AIEC growth and association with the colonic mucosa, even when functional Lcn2 was present." (PMID 36094114, 2022). "In a recently published study, DSS-induced colitis found upregulation of inflammatory-related proteins S100A8, S100A9 (also known as myeloid related protein (MRP) 8 and MRP14), and lipocalin-2 (Lcn2, also known as neutrophil gelatinase-associated lipocalin) in the brain." (PMID 34983592, 2022). "Lcn-2 was used as a biomarker to monitor colitis development." (PMID 35488343, 2022). "Moreover, increasing evidence has indicated the involvement of Lcn2 in the regulation of reshaping gut microbiota in inflammatory bowel disease (IBD) and colitis-associated intestinal inflammation." (PMID 34572499, 2021). "In particular, it was found that GDNPs 2 treatment could reduce lipocalin-2 (Lcn-2) fecal levels in mice with DSS-induced colitis, suggesting an anti-inflammatory role of these nanoparticles; Lcn-2 is considered a biomarker for intestinal inflammation." (PMID 34065193, 2021). "In addition, mice models that were deficient in NOX1 had lowered levels of LCN-2 production and colon damage during TNBS-induced colitis." (PMID 34603464, 2021). "By first using the ank/ank mouse model with progressive ankylosis and subclinical colonic inflammation, confirmed in patients with concurrent AS and IBD, elevated circulating lipocalin 2 levels were associated with the coexisting ankylosis and gut inflammation." (PMID 32188494, 2020). "Moreover, the relationship of murine Lcn2 and peroxisome proliferator-activated receptor gamma (PPARγ) in colitis models and lipid studies reveals a relevant intracellular pathway of aberrant Lcn2 expression regulated by PPARγ." (PMID 32188494, 2020). "The results of this second experiment demonstrated that the signs and symptoms of colitis assessed by measuring body weight and CDAI, and the levels of Lcn2, a biomarker of colon inflammation, were equally attenuated by Vivomixx® and by the Five strains probiotics mixture." (PMID 32629887, 2020). "This is supported by findings showing elevated levels of fecal lipocalin-2 in mice with collagen-induced arthritis and concomitant experimental colitis; induction of colitis delayed the onset of arthritis and reduced its severity as compared with the arthritis-only group." (PMID 30917508, 2019). "Previous articles have reported protective roles of calprotectin and lipocalin 2 against colitis." (PMID 31382637, 2019). "Furthermore, LCN2 plays an important role in gut homeostasis because Lcn2 knockout mice exhibited elevated levels of gut bacteria and inflammation leading to colitis and increased MUP production." (PMID 29459883, 2018). "Finally, we performed a macrophage transfer experiment to elucidate the role of macrophage Lcn2 in the development of spontaneous colitis." (PMID 27734904, 2016). "Furthermore, the fecal concentration of Lcn2 in IL-10 KO mice remarkably increased within a time interval of 12 weeks of colitis induction in the IL-10 KO mice and was significantly positively correlated with the degree of histological inflammation." (PMID 27734904, 2016). "Lcn2 expression in the colonic tissues of IL-10 KO mice increased with the development of colitis." (PMID 27734904, 2016).
colitis (continued). "In addition, the fecal concentration of Lcn2 increased in IL-10 KO mice with the development of colitis, thus supporting the notion that Lcn2 is secreted from colonic epithelial cells in response to inflammatory signals." (PMID 27734904, 2016). "Neutralization of Lcn2 in WT mice resulted in exacerbated DSS-induced colitis." (PMID 27500193, 2016). "Therefore, in the present study, we investigated the role of Lcn2/NGAL in intestinal inflammation using a spontaneous mouse colitis model, interleukin-10 knock out (IL-10 KO) mice." (PMID 27734904, 2016). "Considering that exogenous Lcn2 enhanced autophagic bacterial clearance in macrophages in our in vitro experiments, an intriguing possibility is that Lcn2 secreted from colonic epithelial cells also affects intestinal macrophages to prevent the development of colitis in vivo." (PMID 27734904, 2016). "Finally, we demonstrate that Lcn2-null mice exposed to S. Typhimurium displayed significantly less-severe colitis." (PMID 24465207, 2014). "Thus fecal Lcn-2 is not only a sensitive marker for chemical induced colitis but also reflects severity of inflammation in a well-characterized immune-mediated colitis model." (PMID 22957064, 2012). "Offspring from inulin-fed dams exhibited significantly greater susceptibility to DSS-induced colitis than those from CDD-fed dams, as reflected by greater body weight loss, increased spleen weight, reduced colon weight, and elevated levels of the inflammatory marker fecal lipocalin-2 (LCN2)." (PMID 41133791, 2025). "Episodically elevated Lcn2 may signify short-lived inflammatory events in the Hnf4aΔIEC gut that are self-resolving but can become perpetuated in a subset of animals leading ultimately to the development of colitis." (PMID 37526424, 2023). "However, the protective and pathological roles of Lcn-2 in colitis are still controversial." (PMID 36341389, 2022). "Similarly, Lcn2 was shown to protect from colonic inflammation and intestinal carcinogenesis by controlling the bacterial community composition of the intestinal microbiota in the IL-10 knockout model of colitis." (PMID 34884961, 2021). "The onset of colitis was determined for each mouse on each sampling day with the disease activity index (DAI), encompassing weight loss, stool consistency, and the presence of blood in stools, and these results were complemented by determining increases in fecal lipocalin 2 levels." (PMID 34874778, 2021). "Further, whereas infected Camp+/+ and Camp−/- mice had comparable histopathology, expression of the cell damage marker lipocalin 2 and reductions in cecum weight, only infected Camp+/+ mice displayed increased crypt hyperplasia and decreased colon length as prominent hallmarks of colitis." (PMID 32658599, 2020). "In this study we investigated the extent to which fecal Lcn-2 can serve as a sensitive and non-invasive biomarker of intestinal inflammation using a well-studied murine models of dextran sulfate sodium (DSS) induced colitis and spontaneous colitis in IL-10 deficient mice." (PMID 22957064, 2012). "In the Winnie mouse model of colitis, APX3330 reduced the amount of CD45‐positive leukocytes in the colon and the levels of inflammatory marker, lipocalin‐2 (Lcn‐2), in fecal pellets." (PMID 40746221, 2025). "Fecal lipocalin 2 (LCN2), measured by ELISA, is a non-invasive and well-characterized biomarker of intestinal inflammation in the DSS colitis model." (PMID 37283760, 2023). "Murine colitis-derived intestinal organoids stimulated by LPS show reduced mRNA expression of inflammatory mediators such as TNF-α and lipocalin-2 (LCN2) when treated with quercetin." (PMID 37701897, 2023). "The expression of S100a9, S100a8, Lcn2, Il1f9, Mmp8, and Mmp9 were significantly increased in CD45+ cells from Il17b-/- colitis mice (P < 0.05)." (PMID 36814913, 2023).
colitis (continued). "We therefore tested the expression of AMPs in untreated mice and mice treated with DSS to induce colitis (all samples collected at ZT16, when Reg3g and Lcn2 have been shown to be higher)." (PMID 35223537, 2022). "Both Lcn2 and Reg3g exhibited significantly increased expression in Bmal1+/+ control colon tissue following induction of DSS-colitis." (PMID 35223537, 2022). "We then measured fecal Lipocalin 2 (Lcn-2), a marker of colitis, and found that TLR9−/− mice presented higher levels of fecal Lcn-2 than WT mice." (PMID 35624094, 2022). "Lcn-2 levels gradually elevated from D1-D7 when DSS was present, suggesting that DSS successfully induced colitis." (PMID 35488343, 2022). "Therefore, Lcn-2 may possess a dual function in the pathogenesis of colitis." (PMID 36341389, 2022). "We confirmed upregulation of Lcn2 and S100A9 transcripts and measured increased Lcn2 and S100A8/A9 protein expression in brains isolated from mice with colitis, albeit expression is markedly less than the levels detected in mice injected with LPS." (PMID 34758843, 2021). "Based on our results, Lcn2 and MPO were suitable as biomarkers to differentiate between the 2% and 3% DSS groups, whereas Hgb was sensitive to distinguishing colitis conditions at concentrations below 2% DSS." (PMID 33673349, 2021). "In induced-colitis mice, NMW1 was effective in dampening intestinal inflammation, with significant reductions in disease activity scores, fecal lipocalin-2 levels, pro-inflammatory KC cytokine release, and intestinal epithelial lesion sizes." (PMID 33919372, 2021). "Of note, host antimicrobial gene expression levels (Lcn2, S100a8, S100a9) were similarly upregulated in all DSS-treated mice, and all DSS-treated mice developed similar levels of colitis, as shown by histopathology evaluation of the distal colon." (PMID 34853318, 2021). "We then generated Lcn2/IL-10 DKO mice and compared intestinal inflammation with that of IL-10 KO mice to reveal the role of Lcn2 in the development of colitis." (PMID 27734904, 2016). "Thus, the effect of Lcn2 deficiency on cytokine production from macrophages could not be directly involved in the deteriorated colitis of Lcn2/IL-10 DKO mice." (PMID 27734904, 2016). "Accumulation of Lcn2 stabilizes the metalloproteinase MMP-9 via extracellular binding, which further aggravates the colitis." (PMID 24465207, 2014). "In mice, overexpression of LCN2 leads to severe colitis symptoms, while inhibiting LCN2 does not have this effect." (PMID 41476955, 2025). "GF 129 WT mice receiving HM1, NIMM-g1, or NIMM-g2 fecal transplant did not develop colitis as assessed by colon histology, non-invasive fecal lipocalin-2 (f-LCN2), and tissue inflammatory cytokine levels." (PMID 39113097, 2024). "Our findings suggest that LCN2 specifically regulated ILC3s, particularly the NKp46+ILC3 subgroup, to secrete IL-22 and IL-17A by targeting GPX4, thereby exerting a protective effect on colitis." (PMID 39300068, 2024). "Relevant to this is the fact that in PBS-dosed ADR-159 fed animals we did not detect altered levels of LCN2, which is a proxy for (sub-)colitis inflammation; indicating that we did not observe a pro-inflammatory effect in PBS-dosed ADR-159 fed animals." (PMID 32082288, 2020). "Transfer of IL-10KO-derived, but not DKO-derived, TEPMs prevented the development of colitis in Lcn2/IL-10 DKO mice and these mice exhibited a significantly lower histological score than control mice at 4 weeks of age." (PMID 27734904, 2016). "Other studies report that LCN2 is overexpressed in the intestine in colitis patients and acts as a negative prognostic indicator in colorectal cancer." (PMID 27602760, 2016). "LCN2 is overexpressed in the intestine in colitis patients and acts as a negative prognostic indicator in colorectal cancer." (PMID 26840566, 2016). "LCN2 is produced in response to infection with wildtype but not avirulent S. Tm strains in the streptomycin-colitis model." (PMID 24391500, 2014).